MRE11 (MRE11 double strand break repair nuclease)
Diseases named in the same sentence as MRE11 in open-access papers (continued):
Sharing a sentence is not in itself a finding about the gene and the disease.
rectal cancer (6 papers, 2016 to 2023). A primary or metastatic malignant neoplasm that affects the rectum. "The results revealed that for both right- and left-sided cancers in the TCGA cohort, a high MRE11 expression is associated with a trend towards worse survival, but contrasting data from rectal cancers showed that low MRE11 expression confers worse outcomes." (PMID 37173905, 2023). "Interestingly, high expression of Mre11 was previously shown to be associated with poor prognosis in rectal cancer patients treated with radiotherapy and in patients with right-side localized CRC." (PMID 37372450, 2023). "Accordingly, we previously showed that elevated MRE11 in combination with ATM and MRN complex members was associated with poor outcomes in rectal cancer patients who received neoadjuvant therapy." (PMID 37173905, 2023). "In contrast, for the rectal cancer cohort (TCGA-READ), low MRE11 was significantly associated with poor survival probability (n = 159, p < 0.001)." (PMID 37173905, 2023). "In past studies, we further found that elevated combined expression of MRE11 and ATM or of the entire MRN complex in the TC is associated with a worse prognosis and poor response to neoadjuvant radiotherapy in rectal cancer patients." (PMID 37173905, 2023). "It has been reported that high expression of ATM, especially when combined with MRE11, is associated with worse DFS in rectal cancer treated with neoadjuvant radiotherapy." (PMID 36552003, 2022). "Overall, our findings suggest that the optimal management of rectal cancer requires tailored treatment based on biomarker expression such as the two-protein MRE11/ATM panel described here, as well as clinicopathologic characteristics." (PMID 27930716, 2016). "As a corollary, we proposed that ATM and MRE11 might be used as a predictive marker of radiosensitivity in rectal cancer patients, which would correlate with improved patient outcomes." (PMID 27930716, 2016). "Kaplan-Meier analysis was performed to measure the overall survival (OS) for high (red line) vs. low (blue line) MRE11, NBS1 protein expression in patients with rectal cancer." (PMID 30176843, 2018). "MRE11 and ATM expression were examined in tumor samples from 262 rectal cancer patients who underwent surgery for rectal cancer, including a sub-cohort of 54 patients who were treated with neoadjuvant radiotherapy." (PMID 27930716, 2016). "We investigated the combined expression of MRE11 and ATM as a predictive marker of response to radiotherapy in rectal cancer." (PMID 27930716, 2016). "We have previously shown that the combined expression of two protein markers of MRE11 and ATM may be predictive of patient outcomes in rectal cancer." (PMID 30176843, 2018). "Here, to address this possibility and determine whether MRE11 expression alone holds clinicopathological significance and can predict outcomes in CRC patients, we analyzed samples from 408 individuals with colon and rectal cancer, a subset of which were treated with adjuvant therapy." (PMID 37173905, 2023).
bladder tumor (5 papers, 2014 to 2022). "Is level of DNA repair protein MRE11 in bladder tumors associated with outcomes after bladder-preserving trimodality therapy in patients with muscle-invasive bladder cancer?" (PMID 36383379, 2022). "It has been reported that miR-153 can bind to MRE11, thus, inhibiting its expression in muscle-invasive bladder tumor cells, suggesting a post-transcriptional down-regulation of MRE11A due to miR-153 up-regulation." (PMID 35328651, 2022). "We hypothesized that miR-153 could influence protein levels by inhibiting translation initiation of MRE11 in bladder tumours." (PMID 24625413, 2014).
Immunodeficiency (5 papers, 2010 to 2025). Failure of the immune system to protect the body adequately from infection, due to the absence or insufficiency of some component process or substance. "Germ-line mutations in Mre11 causes ataxia telangiectasia-like disorder (ATLD), a genomic instability syndrome characterised by immunodeficiency, genomic instability, hypersensitivity to radiation and cancer predisposition." (PMID 35853939, 2022). "Hypomorphic mutant mice for Nbs1 or Mre11 exhibit increased radiosensitivity, defective cell cycle checkpoints, chromosome instability and immunodeficiency." (PMID 21054854, 2010). "Due to the various roles MRN has in maintaining the integrity of the genomic DNA, mutations affecting the nuclease activity, structure, or expression levels of MRE11 have been correlated with immunodeficiency, sensitivity to ionizing radiation (IR), and/or oncogenesis." (PMID 32668560, 2020). "Hypomorphic mutations of human MRE11 gene result in ataxia telangiectagia like disorder (ATLD; MIM #604391) characterized by cerebellar atrophy and radiosensitivity without marked immunodeficiency, cancer predisposition or telangiectagia." (PMID 21054854, 2010).
oral cancer (5 papers, 2021 to 2024). "In oral cancer, high MRE11 levels were associated with advanced stage, progression and metastasis and radio- and chemoresistance, as well as reduced OS." (PMID 37894339, 2023). "Larger tumor size, lymph node metastasis, radiotherapy, and high MRE11 expression in cancer tissues were risk factors for decreased overall survival in oral cancer patients, as determined by univariate cox regression analysis." (PMID 33927349, 2021). "High MRE11 expression in oral cancer tissues was associated with larger tumor size, increased lymph node metastasis, and advanced cancer stage." (PMID 33927349, 2021). "MRE11 expression in oral cancer samples was positively associated with tumor size, cancer stage and lymph node metastasis, and was predictive of poorer patient survival and radiotherapy resistance." (PMID 33927349, 2021). "The clinical association of high MRE11 expression with malignant oral cancer behaviors and reduced patient survival prompted us to further explore its role and underlying mechanisms in oral cancer using cell models." (PMID 33927349, 2021). "High MRE11 expression in oral cancer tissues was associated with decreased overall survival following radio- or chemotherapy, indicating a positive correlation with radio- and chemoresistance." (PMID 33927349, 2021). "In addition to IR, we also used CDDP, a chemotherapeutic agent frequently used in oral cancer treatment for its ability to cause DNA damage, to study the effect of MRE11 expression on CDDP-induced cancer cell death." (PMID 33927349, 2021). "In oral cancer, high levels of MRE11 and RAD51 correlated with radiation resistance and poor prognosis." (PMID 37894339, 2023). "The quantitative data of CLN metastasis showed decreased NLN metastasis in mice injected with oral cancer cells with MRE11 knockdown." (PMID 33927349, 2021). "In this study, S473 phosphorylation of AKT was decreased upon MRE11 knockdown but was increased upon MRE11 overexpression in oral cancer cells." (PMID 33927349, 2021). "The effect of MRE11 expression, as determined by immunohistochemistry, was clinically correlated with the outcomes of radiotherapy and chemotherapy in oral cancer patients." (PMID 33927349, 2021). "This is the first study to highlight the significance of MRE11 in oral cancer progression, and adds to the growing body of literature indicating the importance of the chemokine receptor CXCR4 in a multitude of cancers." (PMID 33927349, 2021). "Upstream regulation and overexpression of MRE11 in oral cancer remains one of the key issues to be resolved." (PMID 33927349, 2021). "CXCR4 knockdown also reversed AKT phosphorylation in oral cancer cells induced by MRE11 overexpression." (PMID 33927349, 2021). "Further study using clinical oral cancer specimens confirmed a positive correlation between the expression of MRE11 and S473 phospho-AKT." (PMID 33927349, 2021). "Further western blotting analysis confirmed that CXCR4 expression in oral cancer cells was decreased when MRE11 was knockdowned." (PMID 33927349, 2021). "To downregulate the expression of MRE11 in oral cancer cells, we screened 4 different lentiviral clones and clone 1 showed the highest knockdown efficiency and was used in later knockdown studies." (PMID 33927349, 2021). "MRE11 knockdown decreased, while its overexpression increased, oral cancer cell migration as determined by wound healing assay." (PMID 33927349, 2021). "To study the effect of MRE11 expression on cancer cell metastasis in vivo, we injected the oral cancer cells into the perivitelline space of 2 days old zebrafish embryos." (PMID 33927349, 2021). "MRE11-knockdowned oral cancer cells showed decreased migration into GFP-stained blood vessels, and MRE11-overexpressed oral cancer cells showed increased migration." (PMID 33927349, 2021). "Since MRE11 is a DNA double-strand break repair protein, we addressed its effect on oral cancer cell viability upon IR treatment." (PMID 33927349, 2021).
oral cancer (continued). "MRE11 knockdown in oral cancer cells led to increased expression of FOXA2, which was blocked by cotreatment with SC79, an AKT activator." (PMID 33927349, 2021). "Further survival analyses according to MRE11 protein expression in oral cancer tissues showed that the high MRE11 expression group had decreased overall and progression-free survivals with p values of 0.0002 and 0.04, respectively." (PMID 33927349, 2021). "Herein we report the crucial role of MRE11 in oral cancer progression in a nuclease-independent manner and delineate its key downstream effectors including CXCR4." (PMID 33927349, 2021). "Knockdown of MRE11 decreased the viability of oral cancer cells upon IR while its overexpression resulted in the opposite effect." (PMID 33927349, 2021). "RUNX2 expression was found to be increased by MRE11 in oral cancer." (PMID 37108164, 2023). "Nonetheless, the role of MRE11 in oral cancer remains to be elucidated." (PMID 33927349, 2021). "The effect of MRE11 expression on oral cancer cell metastasis was analyzed in vitro." (PMID 33927349, 2021). "Collectively, MRE11 may serve as a crucial prognostic factor and therapeutic target in oral cancer, displaying dual nuclease dependent and independent roles that permit separate targeting of tumor vulnerabilities in oral cancer treatment." (PMID 33927349, 2021). "In this study, we explored the role of MRE11 in oral cancer behavior in vitro and in vivo, and examined whether MRE11 nuclease activity remains critical to oral cancer progression." (PMID 33927349, 2021). "Knockdown of MRE11 also led to decreased colony formation in oral cancer cells." (PMID 33927349, 2021). "Furthermore, we addressed the possibility that elevated MRE11 expression in oral cancer tissues may be mediated by replication stress in the tumor microenvironment." (PMID 33927349, 2021). "In this study, we conclude that MRE11 may serve as a crucial prognostic factor and therapeutic target in oral cancer, displaying dual nuclease dependent and independent roles that permit separate targeting of tumor vulnerabilities to the DNA damage response and EMT, migration and metastasis." (PMID 33927349, 2021). "In oral cancer (both HSC-3 and Ca9-22 cells), RUNX2 expression was positively regulated by MRE11, the nuclease component of the RAD50/MRE11/NBS1 DNA repair complex." (PMID 37108164, 2023). "Immunohistochemistry analysis also showed a positive correlation between the expression of MRE11 and RUNX2 in oral cancer tissues." (PMID 33927349, 2021). "Studies have shown that the expression of Mre11 in oral cancer tissues is significantly higher than that in adjacent non-cancerous oral tissues and that oral cancers with high MRE11 expression have reduced OS and progression-free survival." (PMID 36338767, 2022). "Mirin is a MRE11 nuclease inhibitor and it induced oral cancer cell death at 25 and 50 μM, but not at 12.5 μM, when compared with untreated controls." (PMID 33927349, 2021). "This was prompted by the observation on cDNA microarray screening that MRE11 RNA expression was significantly elevated in oral cancer tissues compared to adjacent noncancerous oral tissues in the same patients (data not shown)." (PMID 33927349, 2021). "Also, the H129N mutant of MRE11, which is defective in DSB repair, did not inhibit the oral cancer-promoting activities of MRE11." (PMID 33927349, 2021). "To evaluate whether the expression of MRE11 is dysregulated in OSCC, we analyzed its expression in our OSCC gene expression dataset and found that MRE11 mRNA is upregulated in oral cancer tissues (T), in comparison to oral noncancerous tissues (N)." (PMID 33927349, 2021). "However, mirin did not inhibit proliferation or migration in oral cancer cells with MRE11 overexpression." (PMID 33927349, 2021). "However, MRE11 overexpression did not lead to increased cell viability in oral cancer cells." (PMID 33927349, 2021).
oral cancer (continued). "We also observed a negative correlation between the expression of MRE11 and FOXA2 in both oral cancer tissues and metastatic lymph nodes, and a negative correlation between the expression of S473 phospho-AKT and FOXA2." (PMID 33927349, 2021).
ovarian tumor (5 papers, 2018 to 2025). "PRDX1 interacted with the MRN complex, and we previously showed that high MRE11 expression in ovarian tumors is linked to an aggressive phenotype and predicts platinum resistance." (PMID 40387816, 2025). "In a clinical cohort of human ovarian tumours, low levels of BRCA2 expression with high levels of MRE11 co-expression were linked with worse progression-free survival (PFS) (p = 0.005) and overall survival (OS) (p = 0.001)." (PMID 37446144, 2023). "Whilst nuclear Mre11 may lead to increased DNA repair capacity and promote platinum resistance, we also observed cytoplasmic staining for MRE11 in ovarian tumours." (PMID 35853939, 2022).
triple-negative breast carcinoma (5 papers, 2019 to 2025). An invasive breast carcinoma which is negative for expression of estrogen receptor (ER), progesterone receptor (PR), and human epidermal growth factor receptor 2 (HER2). "In a subset of triple-negative breast cancer cells, the double-strand break repair protein MRE11 is mutated." (PMID 37108225, 2023). "Recently Gupta and colleagues showed an association between triple negative breast cancer and MRE11 defects." (PMID 31395037, 2019). "For example, the E3 ligase RNF126 ubiquitinates MRE11, thereby activating the DNA damage response in triple-negative breast cancer and contributing to resistance to radiotherapy." (PMID 40697329, 2025). "Notably, miR-493-5P also decreased Mre-11 activity, which not only impairs homologous recombination but may further induce R-loop accrual in triple-negative breast cancer cells." (PMID 37108225, 2023).
viral infection (5 papers, 2018 to 2023). "Each mutant virus infection abrogates degradation of known substrates RAD50 and MRE11." (PMID 34463575, 2021). "In the presence of bortezomib, the degradation of Tab182 and MRE11 following viral infection was reduced but not completely inhibited; in the absence of the proteasome inhibitor (DMSO), the proteins were degraded in the presence of the viruses." (PMID 29593045, 2018). "Possessing endonuclease and exonuclease activities, MRE11 is the core of the MRN complex and is essential in early DSB recognition and signaling, cell cycle checkpoint regulation, telomere maintenance, DNA recombination, meiosis, and immune response to viral infections." (PMID 37894339, 2023).
anemia (4 papers, 2022 to 2025). A reduction in the number of red blood cells, the amount of hemoglobin, and/or the volume of packed red blood cells. "Mammalian RAD51, in collaboration with BRCA1, BRCA2, and Fanconi anemia proteins, plays a critical role in preventing nascent DNA degradation by MRE11." (PMID 40737093, 2025). "It relies on several proteins including BRCA1 and BRCA2, proteins of the Mre11-Rad50- Nbs1 (MRN) complex, CtIP, MRE11, RAD51, ATM, H2AX, PALB2, RPA, RAD52, and the Fanconi anemia pathway proteins." (PMID 39678373, 2024).
Ataxia (4 papers, 2011 to 2021). Ataxia refers to impaired coordination of voluntary muscle movement. "Another possibility that causes cerebellar atrophy and ataxia in Nbs1- CNSΔ, Mre11-CNSΔ, or Atr- CNSΔ could be due to the impact of DDR defect in surrounding cells of Purkinje cells or neurons." (PMID 35153719, 2021). "MRE11 mutations cause the A-TLD syndrome, which, by its definition, shows cerebellar defects and ataxia." (PMID 35153719, 2021). "In individuals with ataxia-causing MRE11 mutations, MRE11 fails to effectively form a complex and recruit ATM." (PMID 25055202, 2014). "Lack of mutations in APTX, SETX and MRE11 genes in the third family diagnosed with ataxia and oculomotor apraxia and no cerebellar atrophy suggests the involvement of another mechanism for the development of this disorder." (PMID 21324166, 2011). "We screened nine affected individuals from 4 families with ataxia and oculomotor apraxia for mutations in the reported genes APTX, SETX and MRE11 and identified a novel truncating mutation in SETX gene in one family and a previously reported missense mutation in MRE11 gene in two families." (PMID 21324166, 2011). "The observations that deletion of Nbs1 or Mre11 in Purkinje cells do not phenocopy cerebellar degeneration and ataxia in human A-TLD patients are surprising." (PMID 35153719, 2021). "Additionally, although NBS1 and MRE11 function together mainly to activate ATM and repair DSBs, only A-TLD, but not NBS, patients show ataxia, suggesting a different yet unknown function of each component of the MRN complex controlling cerebellar development or the function of Purkinje cells." (PMID 35153719, 2021).
B-cell lymphomas (4 papers, 2016 to 2023). "To first examine the role of Mre11 in class switching, we utilized two different short hairpin RNAs (shRNA) expressed from lentiviral vectors to silence its expression in mouse mature B cell lymphoma cell line CH12F3 that can be stimulated to specifically undergo isotype switching to IgA." (PMID 34926456, 2021).
breast tumor (4 papers, 2014 to 2026). "MRE11, a breast tumor suppressor and component of the MRE11-RAD50-NBS1 complex, plays a critical role in DNA end resection and initiation of ataxia-telangiectasia mutation-dependent (ATM-dependent) DNA damage signaling." (PMID 41505211, 2026). "Here, we found that MRE11 is deacetylated by the SIRT2 sirtuin deacetylase and breast tumor suppressor, which promotes DNA binding to facilitate DNA end resection and ATM-dependent signaling." (PMID 41505211, 2026).
leukemia (4 papers, 2007 to 2026). A malignant (clonal) hematologic disorder, involving hematopoietic stem cells and characterized by the presence of primitive or atypical myeloid or lymphoid cells in the bone marrow and the blood. "We estimated the frequency of constitutional mutations and polymorphisms in selected regions of MRE11, RAD50, and NBN in the group of 220 children diagnosed with childhood leukemias and controls (n=504/2200)." (PMID 24093751, 2013). "Abnormalities in a complex containing the BRCA pathway proteins MRE11, Rad50 and NBS1 (MRN complex) also associate with leukemia and lymphoma." (PMID 17683622, 2007). "Therefore it was interesting to question whether also MRE11 and RAD50 germline mutations may increase the risk for childhood leukemia." (PMID 24093751, 2013).